CDKN2B (cyclin dependent kinase inhibitor 2B)
Diseases named in the same sentence as CDKN2B in open-access papers (continued):
Sharing a sentence is not in itself a finding about the gene and the disease.
coronary atherosclerosis (2 papers, 2018 to 2020). Atherosclerosis of the coronary vasculature. "For example, PheWAS replicated the associations for four functional SNPs in the gene CDKN2B − AS1 to coronary atherosclerosis." (PMID 29378629, 2018). "Genome-wide analysis of patients with hereditary coronary atherosclerosis indicated that the 9p21.3 allele variant was associated with AS burden, and loss of cyclin-dependent kinase inhibitor 2B (CDKN2B) at this locus promotes vascular SMC apoptosis and aneurysm progression." (PMID 33597922, 2020).
cutaneous melanoma (2 papers, 2024). A primary melanoma arising from atypical melanocytes in the skin. "The genes most recurrently affected by BA-SVs in cutaneous melanomas were CDKN2A and CDKN2B, with the majority being deletion events." (PMID 38758740, 2024).
endometriosis (2 papers, 2018). The growth of functional endometrial tissue in anatomic sites outside the uterine body. "(i) Cyclin-dependent kinase inhibitor 2B (CDKN2B), whose rs1537377 polymorphism showed significant associations with endometriosis, was found in other studies to play a key role in the pathogenesis." (PMID 29750165, 2018). "Genetic differences play a significant role in risk for endometriosis; a recent meta-analysis of over 170,000 endometriosis patients and almost 200,000 controls revealed 14 genetic regions of interest, including WNT4, GREB1, IL1A, and CDKN2B." (PMID 30134794, 2018).
endothelial dysfunction (2 papers, 2019 to 2026). In vascular diseases, endothelial dysfunction is a systemic pathological state of the endothelium (the inner lining of blood vessels) and can be broadly defined as an imbalance between vasodilating and vasoconstricting substances produced by (or acting on) the endothelium.
familial atypical multiple mole melanoma syndrome (2 papers, 2024 to 2025). "Germline 9p21.3 deletions involving the contiguous CDKN2A/CDKN2B/ANRIL region exhibit cancer predisposition syndrome with characteristics overlapping NF1, familial atypical multiple mole melanoma syndrome (FAMMM), and Li–Fraumeni syndrome (LFS)." (PMID 40046620, 2025).
Hypertension (2 papers, 2020 to 2025). The presence of chronic increased pressure in the systemic arterial system. "CDKN2B anti-sense RNA (CDKN2B-AS1) spans about 126.3 kb andoverlaps with CDKN2B (p15) at the 5’ end and comprises of 20 exonsthat are prone to alternative splicing (Jarinovaet al., 2009) and reported to be linked to CAD risk,hypertension and stroke (Bai etal., 2014)." (PMID 32191788, 2020).
ischemic stroke (2 papers, 2016 to 2022). A stroke disorder caused by obstruction of blood flow to the brain, due to thrombotic (local blood clot formation) or embolic (due to a blood clot or other material traveling from another site) event. "For example, DNA methylation of Cyclin-dependent kinase inhibitor 2B (CDKN2B) has been showcased to promote an increased risk of arterial calcification in ischemic stroke patients." (PMID 36312038, 2022).
liposarcoma (2 papers, 2017 to 2022). A usually painless malignant tumor that arises from adipose tissue. "The expression of two inhibitors of Cdk4, Cdkn2a and Cdkn2b, was significantly increased, as a late event, present only in DAKO liposarcomas." (PMID 28459858, 2017).
metastatic melanoma (2 papers, 2010 to 2021). A melanoma that has spread from its primary site to another anatomic site. "CYT-high metastatic melanomas had recurrent copy number amplifications in loci 1p12 (NOTCH2), 1q44 (OR2M4), 7q36.1 (KCNH2), 11q13.3 (FGF3/4), 12p11.23 (MED21) and 12q13.3 (R3HDM2) and deletions in 1p22.1 (RHOC, NRAS), 9p21.3 (CDKN2B), 10q23.2 (miR346), 11q23.3 (ATM, CHEK1, ETS1) and 15q15.3 (CASC4)." (PMID 33779796, 2021).
myeloid leukemia (2 papers, 2017 to 2019). A clonal proliferation of myeloid cells and their precursors in the bone marrow, peripheral blood, and spleen. "Loss of expression of CDKN2B accelerates the development of myeloid leukemia in transgenic mice." (PMID 28261562, 2017).
parathyroid tumors (2 papers, 2017 to 2022). "Also, our study shows that the transcriptional silencing of CDKN2A and CDKN2B due to hypermethylation in at least 50% of sporadic parathyroid tumors." (PMID 28600574, 2017). "In parathyroid tumors, the hypermethylation of the tumor-suppressor HIC1, together with RASSF1A, CDKN2B and APC genes, were described in PCas and could be an early event in parathyroid tumor development." (PMID 35586620, 2022).
peritoneal mesothelioma (2 papers, 2022 to 2023). A benign or malignant mesothelial neoplasm that arises from the peritoneum. "Furthermore, in the peritoneal mesothelioma cohort in the previously cited study, the most common alterations detected in peritoneal mesothelioma were inactivating mutations in BAP1 (47.9%), NF2 (26.5%), CDKN2A (25.9%), CDKN2B (19.5%) and PBRM1 (15.8%)." (PMID 38136262, 2023). "The five most frequently altered genes in pleural mesothelioma were CDKN2A (48.2%), BAP1 (45.0%), CDKN2B (42.2%), NF2 (32.8%) and MTAP (32.3%), in peritoneal mesothelioma BAP1 (47.9%), NF2 (26.5%), CDKN2A (25.9%), CDKN2B (19.5%), PBRM1 (15.8%)." (PMID 36138075, 2022).
pituitary adenomas (2 papers, 2014 to 2016). "Finally, the role of p19, encoded by Cdkn2b, as a tumour suppressor in regulating pituitary anterior lobe proliferation has been revealed by a conventional knockout mouse model of Cdkn2b, as Cdkn2b−/− mice developed multiple tumour types including PRL, GH and FSH secreting pituitary adenomas." (PMID 26320859, 2016).
psoriasis (2 papers, 2018 to 2022). An autoimmune condition characterized by red, well-delineated plaques with silvery scales that are usually on the extensor surfaces and scalp. "The assay showed that the expression of CDKN2B was obviously repressed in psoriatic epidermis, which coincided with the increase of epidermal miR-17-92 cluster in psoriasis." (PMID 29752469, 2018). "We additionally examined the protein levels of CDKN2B and SOCS1, the two target genes responsible for the effects of miR-17-92 cluster on keratinocytes, in the skin specimens from five psoriasis patients and five healthy controls using immunofluorescence." (PMID 29752469, 2018).
renal carcinoma (2 papers, 2019 to 2022). A carcinoma arising from the epithelium of the renal parenchyma or the renal pelvis. "Although we did find three VUS’s in BAP1 in three families and a pathogenic variant in MITF in one family, pathogenic germline variants in BAP1, MITF or CDKN2B are not frequent causes of hereditary renal cancer in Denmark." (PMID 31034483, 2019). "The results of the study indicate that germline variants in BAP1, MITF and CDKN2B are not frequent in Danish families with suspected hereditary predisposition to renal cancer, and in the families of this study a possible genetic background of RCC is still unresolved." (PMID 31034483, 2019).
urothelial carcinoma (2 papers, 2021 to 2026). A malignant neoplasm derived from the transitional epithelium of the urinary tract (urinary bladder, ureter, urethra, or renal pelvis). "Deletion of CDKN2A/CDKN2B genes in urothelial carcinoma were found to be a common event and have been shown to be a crucial event in the progression from normal urothelium to carcinoma." (PMID 34127009, 2021). "The somatic alterations were consistent with previous reports of urothelial carcinoma, including homozygous deletions of CDKN2A and CDKN2B." (PMID 41800036, 2026).
acromegaly (1 paper, 2020). Acromegaly is an acquired disorder related to excessive production of growth hormone (GH) and characterized by progressive somatic disfigurement (mainly involving the face and extremities) and systemic manifestations. "Sixteen patients with acromegaly and PHP underwent rigorous genetic testing with DNA sequence analysis performed for genes including: MEN1, CDC73, CDKN1A, CDKN1B, CDKN2B, CDKN2C, and AIP, as well as MLPA to search for deletions or duplications in MEN1, CDC73, CDKN1B, and AIP genes." (PMID 32311048, 2020).
actinic keratosis (1 paper, 2015). A precancerous lesion of the skin composed of atypical keratinocytes. "Altered expression of CDKN2B (p15INK4b) mRNA level and new mutations have been detected in patients with actinic keratosis (AK) suggesting its possible role in AK development." (PMID 26121660, 2015).
acute leukemia (1 paper, 2019). A clonal (malignant) hematopoietic disorder with an acute onset, affecting the bone marrow and the peripheral blood. "In acute leukemias, homozygous deletion of CDKN2B and CDKN2A occurs in approximately 30% of ALL patients." (PMID 30635552, 2019).
age-related macular degeneration (1 paper, 2022). Age-related loss of vision in the central portion of the retina (macula), secondary to retinal degeneration. "One study reported the association of a CpG site at CDKN2B in normal-tension glaucoma, another study found CpG sites at SKI and GTF2H4 in the retinal pigment epithelium of age-related macular degeneration patients." (PMID 35741817, 2022).
astrocytic tumor (1 paper, 2015). A glial tumor of the brain or spinal cord showing astrocytic differentiation. "With regard to CDKN2B, a few studies have investigated its expression in astrocytic tumors, indicating that the known mechanisms that can change its expression are loss of heterozygosity (LOH), homozygous deletion, point mutations, and hypermethylation of the promoter region." (PMID 26317630, 2015). "Therefore, the present study aimed to evaluate the expression and methylation profiles of the genes CDKN2A, CDKN2B, CDC6, Bmi-1, CCND1, and RB1 in astrocytic tumors in the northern region of Brazil." (PMID 26317630, 2015).
benign parathyroid tumors (1 paper, 2022). "Other specific genes whose pathways are linked to the development of parathyroid tumors, such as RIZ1, APC, RASSF1A, CDKN2A/p16, CDKN2B/p15, RB1, WT1, GATA4, PYCARD, SFRP1 and SFRP2, also appeared to be hypermethylated in both malignant and benign parathyroid tumors." (PMID 35628190, 2022).
bile duct cancer (1 paper, 2022). "The methylation profile of the CDKN2B promoter, a cell cycle inhibitor gene, was reduced in cells overexpressing miR‐29b that inhibits bile duct cancer progression by releasing DNMT3B‐mediated inhibition of CDKN2B expression." (PMID 34970791, 2022).
breast DLBCL (1 paper, 2023). "The most frequently observed mutations in breast DLBCL were CDKN2A and CDKN2B loss, which was found simultaneously in five of seven cases." (PMID 37706649, 2023).
cerebellar ataxia (1 paper, 2023). A neurological syndrome characterized by clumsy and uncoordinated movement of the limbs, trunk, and cranial muscles. "In addition, mRNAs, such as cyclin dependent kinase inhibitor 2B (CDKN2B) is associated with cell growth and death, and FERM domain containing 4B (FRMD4B) is associated with corpus callosum agenesis with facial anomalies and cerebellar ataxia." (PMID 37663277, 2023).
childhood leukemia (1 paper, 2023). An acute or chronic leukemia that occurs during childhood. "Therefore, mutations in CDKN2A (− 222 T>A) and CDKN2B (593A>T, C) may play a role in susceptibility to childhood leukemia." (PMID 37314514, 2023).
chronic cervicitis (1 paper, 2024). Chronic inflammation of the cervix. "We used a set of patient-derived precancerous (n = 32) and noncancerous (chronic cervicitis; n = 10) tissue samples to investigate the gene expression of several OIS (LMNB1, CDKN2A, CDKN2B, and CDKN1A), and SASP (IL1A, CCL2, TGFB1, CXCL8, and MMP9) biomarkers using qRT-PCR." (PMID 39727946, 2024).
clear cell carcinoma (1 paper, 2012). "Clear cell carcinoma samples exhibited a higher frequency of CDKN2B promoter hypermethylation compared to those of other histological types (P=0.05)." (PMID 23226780, 2012). "Methylation of the CDKN2B gene was more frequent in clear cell carcinoma than other histological types (P=0.049)." (PMID 23226780, 2012). "However, we found a statistically borderline correlation between CDKN2B methylation and clear cell carcinoma." (PMID 23226780, 2012). "In our study, all the clear cell carcinoma samples showed methylation of the CDKN2B gene promoter." (PMID 23226780, 2012).
CNS DLBCL (1 paper, 2021). "Although not included in this study, our NGS results for CNS DLBCL had a higher 9p21 (including CDKN2A and CDKN2B) loss ratio (13/17, 76.5%) than DLBCL NOS (43/154, 27.9%)." (PMID 34461835, 2021).
ductal breast carcinoma (1 paper, 2012). "In particular, CDKN2B methylation was more common in lobular than ductal breast carcinoma at a borderline level of significance (10/22, 45% versus 14/64, 22% with all groups included, P = 0.052 by Fisher's test)." (PMID 22691310, 2012).
endometrial adenocarcinoma (1 paper, 2025). "The second case was a chemotherapy-refractory, CDKN2B-deleted metastatic endometrial adenocarcinoma treated with abemaciclib as third-line therapy." (PMID 39177668, 2025).
ependymoma (1 paper, 2009). A WHO grade II, slow growing tumor of children and young adults, usually located intraventricularly. "The tumors suppressor genes RASSF1, CDKN2A, CDKN2B, p14ARF and TP73, as well as other genes potentially involved in the tumorigenesis of ependymomas, such as CASP1, MGMT, TIMP3 and THBS1 are epigenetically silenced by aberrant promoter methylation in subsets of ependymomas." (PMID 19333441, 2009).
fibrosis (1 paper, 2023). the formation of excess fibrous connective tissue in an organ or tissue in a reparative or reactive process. "However, changes in the methylation level of the “driver” genes for oncopathology (АРС, CDKN2B, GSTP1, ELF4, TERT, WT1) are registered in tumor tissue in the setting of liver cirrhosis but not fibrosis." (PMID 36923478, 2023).
ganglioglioma (1 paper, 2023). A well differentiated, slow growing neuroepithelial neoplasm composed of neoplastic, mature ganglion cells and neoplastic glial cells. "CDKN2A (and adjacent CDKN2B) loss has been previously identified in a small minority of gangliogliomas as well as in other pediatric CNS tumors, such as pleomorphic xanthroastrocytoma (where CDKN2A/B loss is typical)." (PMID 36966348, 2023).
hemorrhage (1 paper, 2024). Loss of blood from the vascular compartment to the exterior or into nonvascular body space as a result of rupture or severance of the blood vessels. "Molecular analysis indicated that CDKN2B, KMT5B, and PIK3CA alteration occurred more in the hemorrhage group (CDKN2B, 84.4% vs. 62.2%, p = 0.029; KMT5B, 25.0% vs. 8.9%, p = 0.029; and PIK3CA, 81.3% vs. 58.5%, p = 0.029)." (PMID 38877400, 2024). "CDKN2B, KMT5B, and PIK3CA alterations were common in the hemorrhage group, suggesting a possible mechanism for the prognostic value of intratumoral hemorrhage." (PMID 38877400, 2024).
HIV-1 infection (1 paper, 2011). The type species of lentivirus and the etiologic agent of acquired immunodeficiency syndrome (AIDS). "Three of these genes baculoviral IAP repeat containing 2 (Birc2), Myc and FN1 are strongly down-regulated, and CDKN2A, CDKN2B and BRAC1 are moderately down-regulated during acute HIV-1 infection." (PMID 21533265, 2011).
Hyperglycemia (1 paper, 2020). An increased concentration of glucose in the blood. "Data indicated that decreased DNA methylation levelsat CpG sites in the CDKN2A and CDKN2B gene promoterin pancreatic islets of the rat offspring were associatedwith maternal hyperglycemia." (PMID 31721535, 2020). "This gives rise to thespeculation that maternal hyperglycemia may change thenormal DNA methylation pattern of cell cycle inhibitorygenes CDKN2A and CDKN2B in pancreatic islets of ratoffspring." (PMID 31721535, 2020).
hypopharyngeal carcinoma (1 paper, 2017). Carcinoma, predominantly squamous cell, arising from the epithelial cells of the hypopharynx. "In this study, CDKN2A was found down-regulated expression (61.0%) and point mutation (4.5%), suggesting CDKN2A and CDKN2B deficiency and inactivation may contribute to hypopharyngeal carcinoma progression." (PMID 29156722, 2017). "Moreover, we identified several copy number variants (CNVs) genes were associated with hypopharyngeal carcinoma, one with amplification (ATF1) and two with deletions (CDKN2A, CDKN2B)." (PMID 29156722, 2017).
hypospadias (1 paper, 2025). Hypospadias is the displacement of the urethral meatus on the ventrum of the penis. "RNA-seq and WGCNA identified 11 differentially expressed genes, among which CDKN2B showed a marked downregulation in hypospadias samples." (PMID 41595569, 2025). "The CDKN2B-TGF/Smad axis may represent a central pathway linking VSMC phenotypic switching to abnormal vascular remodeling in hypospadias." (PMID 41595569, 2025).
idiopathic pulmonary fibrosis (1 paper, 2025). Idiopathic pulmonary fibrosis (IPF) is a nonneoplastic pulmonary disease that is characterized by the formation of scar tissue within the lungs in the absence of any known cause. "CDKN2B encodes a protein that inhibits cell cycle progression and has been associated with idiopathic pulmonary fibrosis and amplifies sepsis-induced lung injury." (PMID 40822650, 2025).
injury (1 paper, 2021). Damage inflicted on the body as the direct or indirect result of an external force, with or without disruption of structural continuity. "In terms of interaction with serious complications in COVID‐19 patients, 6 markers (MFAP4, ECM1, CDKN2B.AS1, CAPN2, FGG, and CD147) and 2 exRNAs (SNORD33 and miR‐122‐5p) are involved in thrombosis or liver injury." (PMID 34122778, 2021).
Insulin resistance (1 paper, 2009). Increased resistance towards insulin, that is, diminished effectiveness of insulin in reducing blood glucose levels. "Interaction between CDKN2B rs10811661 and TCF7L2 rs4506565 variants were significant (β = 1.6667, p = 0.0002, 0.0341, and 0.0012 for main and interacting effects), and it was associated with high slope values, which may be expressed as an increase in insulin resistance across ages." (PMID 20018066, 2009).
kidney cancer (1 paper, 2014). Primary or metastatic malignant neoplasm involving the kidney. "We used quantitative RT‐PCR to measure the levels of three TGF‐beta pathway components (TGFB2, INHBA, and SMAD3) and two TGF‐beta targets (THBS1 and CDKN2B) which were previously found to be significantly lower in FLCN‐deficient kidney cancer cells and tumors." (PMID 25121506, 2014).
kidney clear cell carcinoma (1 paper, 2015). "This is consistent with our finding of recurrent CDKN2A and CDKN2B deletions in CIMP+ samples from KIRC patients mentioned earlier, which were independently linked to a more clinically aggressive phenotype of kidney clear cell carcinoma." (PMID 25960768, 2015).
lipoma (1 paper, 2021). A benign, usually painless, well-circumscribed lipomatous tumor composed of adipose tissue. "We detected an upregulation of senescence markers p21 and HIPK2 but not CDKN2B (p15) in high-passage compared with low-passage cells from lipomas of patients with PHTS (LipPD1)." (PMID 34273354, 2021).
lymph node metastasis (1 paper, 2023). "Additionally, children with CDKN2B rs2069426 mutation were more likely to have lymph node metastasis." (PMID 37314514, 2023). "However, children with CDKN2B rs2069426 mutations were more likely to have lymph node metastasis." (PMID 37314514, 2023). "In contrast, CDKN2B rs2069426 was more likely to develop lymph node metastasis (P = 0.017)." (PMID 37314514, 2023).